CSMD2 (CUB and Sushi multiple domains 2)
Synonyms: KIAA1884; dJ1007G16.1; dJ1007G16.2; dJ947L8.1
Tractability: Antibody: UniProt places it where antibodies can reach, with high confidence; UniProt predicts a signal peptide or a membrane-spanning region; its Gene Ontology location is reachable by antibodies, with medium confidence. PROTAC: its protein half-life has been measured.
Gene: Protein-coding gene on chromosome 1 (33,513,998 to 34,165,842, reverse strand). Ensembl gene ENSG00000121904.
Subcellular location: Cell membrane
Gene Ontology:
Biological process: maintenance of postsynaptic density structure; postsynaptic density assembly
Cellular component: glutamatergic synapse; plasma membrane; postsynaptic density membrane
Genetic constraint (gnomAD): Loss-of-function variants: 111 observed, 357.46 expected, observed/expected ratio (o/e) 0.31, 90% interval 0.26 to 0.36. The upper end of that interval is the gene's LOEUF score, 0.36, which puts it in group 1 of 6, group 1 being the genes least tolerant of losing a copy. Missense variants: 3,638 observed, 4,661.8 expected, observed/expected ratio (o/e) 0.78, 90% interval 0.76 to 0.8. Synonymous variants: 1,756 observed, 1,878 expected, observed/expected ratio (o/e) 0.94, 90% interval 0.9 to 0.97.
Homologues: Orthologues: chimpanzee CSMD2 (99% identical), macaque CSMD2 (98% identical), rabbit CSMD2 (96% identical), mouse Csmd2 (95% identical), rat Csmd2 (94% identical), guinea pig CSMD2 (94% identical), dog CSMD2 (94% identical), tropical clawed frog csmd2 (78% identical). Paralogues in human: CSMD1 (64% identical), CSMD3 (59% identical), SVEP1 (22% identical), CR1 (11% identical), CR2 (8% identical), SEZ6 (6% identical), SEZ6L (6% identical), PAPPA2 (6% identical), SEZ6L2 (5% identical), SELP (5% identical), CFH (5% identical), PAPPA (5% identical), and 27 more.
Diseases named in the same sentence as CSMD2 in open-access papers:
CSMD2 is named in the same sentence as 26 diseases in open-access papers, as found by Europe PMC text mining. Sharing a sentence is not in itself a finding about the gene and the disease. The quoted sentences say what the papers report.
colorectal cancer (6 papers, 2017 to 2023). A primary or metastatic malignant neoplasm that affects the colon or rectum. "Particularly, CSMD2, a candidate tumor suppressor gene in colorectal cancer and breast cancer patients was mutated in three metastatic ACC samples." (PMID 30301885, 2018). "CSMD2 was reported to be a tumor suppressor, its low expression was significantly associated with differentiation, lymphatic invasion, tumor size, and the poor prognosis of colorectal cancer patients." (PMID 33680913, 2020). "CSMD2 encoding a member of the C1r/C1s, Uegf, Bmp1 (CUB) and sushi multiple domain protein (CSMD) family – is a candidate TSG associated with colorectal cancer." (PMID 31200735, 2019). "CSMD2 may act as a tumor suppressor gene for colorectal cancer." (PMID 33557409, 2021).
schizophrenia (3 papers, 2013 to 2020). A major psychotic disorder characterized by abnormalities in the perception or expression of reality. "For example, exonic deletions in the neurodevelopmental gene AUTS2 are often associated with cognitive deficits, and variants in CSMD2 have been associated with comorbidity of depression and alcohol dependence, and schizophrenia." (PMID 26829228, 2016).
lung carcinoma (2 papers, 2020 to 2021).
adrenocortical carcinoma (1 paper, 2022). "KIAA0100 and CSMD2 are frequently mutated during metastasis in adrenocortical carcinoma." (PMID 36476508, 2022).
Anxiety (1 paper, 2021). Intense feelings of nervousness, tension, or panic often arise in response to interpersonal stresses. "A role for Abl2, Csmd2, Dlgap1, and Isl1 in neurodevelopment and psychiatric and neurodegenerative diseases have been reported in previous studies and our association analysis suggests a role in anxiety." (PMID 33431988, 2021).
esophageal carcinoma (1 paper, 2022). A primary or metastatic malignant neoplasm involving the esophagus. "CSMD2 expression was negatively correlated with TMB and MSI in stomach adenocarcinoma (STAD) and stomach and esophageal carcinoma (STES), as well as with tumor mutational burden, microsatellite instability, and TNB in head-neck squamous cell carcinoma (HNSC)." (PMID 36061177, 2022).
gastric cancer (1 paper, 2022). A primary or metastatic malignant neoplasm involving the stomach. "It had moderate or high diagnostic efficacy, and the high expression was related to a higher stage and poor prognosis, for example, the expression level of CSMD2 was high in gastric cancer, and patients with high CSMD2 expression had poor prognosis." (PMID 36061177, 2022).
Kawasaki disease (1 paper, 2023). A rare inflammatory disease characterized by an acute febrile, systemic, self-limiting, medium-vessel vasculitis primarily affecting children. "Thus, for patients with Kawasaki disease, a mutation altering CSMD2 may promote a hyper inflammatory response." (PMID 38259468, 2023).
sudden cardiac arrest (1 paper, 2011). Unexpected rapid natural death due to cardiovascular collapse within one hour of initial symptoms. "We also assessed 4 recently published gene associations for sudden cardiac arrest, validating NOS1AP (p = 4.50 × 10-2, OR = 1.15, 95% CI:1.003, 1.326), CSMD2 (p = 6.6 × 10-3, OR = 2.27, 95% CI:1.681, 2.859), and AGTR1 (p = 3.00 × 10-3, OR = 1.13, 95% CI:1.042, 1.215)." (PMID 21658281, 2011).
cancer (12 papers, 2016 to 2024). A tumor composed of atypical neoplastic, often pleomorphic cells that invade other tissues. "Further, in many cancer types, CSMD2 expression is upregulated and is associated with a higher stage and poor prognosis." (PMID 38259468, 2023). "In this study, the expression of CSMD2 was examined and its diagnostic efficacy and prognostic value in pan-cancer were explored." (PMID 36061177, 2022). "The levels of cancer-associated fibroblasts (CAFs) and endothelial cells were positively correlated with CSMD2 expression in most cancers." (PMID 36061177, 2022). "In most cancers, CSMD2 might be associated with immune evasion or immunosuppression, as deficient anti-tumor immunity and upregulation of immune checkpoints were also observed in this study." (PMID 36061177, 2022). "We also explored the diagnostic value of CSMD2 as an independent biomarker for pan-cancers." (PMID 36061177, 2022). "In conclusion, CSMD2 could serve as a promising prognostic, diagnostic and immune biomarker in pan-cancer." (PMID 36061177, 2022). "In most cancers, CSMD2 was associated with immune evasion or immunosuppression." (PMID 36061177, 2022). "In summary, hypermethylation of CSMD2 promoter and high levels of m6A methylation regulators have been observed in most cancers." (PMID 36061177, 2022). "The heatmap indicated that CSMD2 mRNA was positively correlated with most m6A methylation regulatory factors in most cancers." (PMID 36061177, 2022). "The results showed that the expression of CSMD2 was inconsistent in 33 types of cancers, of which CSMD2 expression was upregulated in most tumors." (PMID 36061177, 2022). "The frequency and types of genetic alterations of CSMD2 in 32 cancer studies were further investigated." (PMID 36061177, 2022). "Ultimately, we observed with a pan-cancer analysis that CSMD2 was upregulated in most tumors and had moderate to high diagnostic efficiency, and that high expression was closely associated with poor prognosis in patients with tumors." (PMID 36061177, 2022). "Further clinical correlation analysis showed that CSMD2 alterations were related to the survival of patients with cancer." (PMID 36061177, 2022). "However, current scientific evidence on the comprehensive roles of CSMD2 in pan-cancer is relatively scarce." (PMID 36061177, 2022). "Furthermore, we analyzed the potential relationship between genetic alterations in CSMD2 and the prognosis in patients with different cancer." (PMID 36061177, 2022). "Our results showed that CSMD2 expression was positively correlated with m6A methylation regulatory factors, and implied that m6A methylation levels might be positively correlated with CSMD2 expression in pan-cancer." (PMID 36061177, 2022). "Moreover, hypermethylation of CSMD2 promoter and high levels of m6A methylation regulators were also observed in most cancers." (PMID 36061177, 2022). "While CSMD2 has a tumour suppressive role in several cancers, CSMD2 mutations in HNSCC have not been described previously." (PMID 27693639, 2016). "Additionally, we analyzed the correlation between epigenetic methylation and CSMD2 expression in various cancers based on UALCAN, as well as, the correlation between CSMD2 and tumor mutational burden (TMB), microsatellite instability (MSI), and tumor neoantigen burden (TNB) in tumors." (PMID 36061177, 2022). "Here, we performed further analyses and characterization of HBV integrations identified by our recently reported VIcaller platform in recurrent or known HCC genes (such as TERT, MLL4, and CCNE1) as well as non-recurrent cancer-related genes (such as CSMD2, NKD2, and RHOU)." (PMID 33557409, 2021). "Statistically significant differences in CSMD2 expression were observed based on different pathological stages in BLCA, ESCA, and KIRP, but not in other cancers." (PMID 36061177, 2022).
cancer (continued). "The integration sites at the two hotspots, chr1: 34,397,059 (CSMD2) and chr8:118,557,327 (MED30/EXT1), were not reported in previous HBV integration studies (except in this dataset as we previously reported), but overlapped with multiple fusion events from both cancer cell lines and TCGA." (PMID 35710421, 2022).
tumor (11 papers, 2016 to 2025). "CSMD1 and CSMD2, which encode inhibitors of the complement system, have been proposed as tumor suppressor genes, with CSMD1 being the second most frequently mutated gene in BCC." (PMID 40725190, 2025). "Reduced CSMD2 expression was linked to tumour size, lymphatic invasion, and differentiation in colon cancer, the development of pulmonary sarcomatoid carcinoma, liver metastasis, and pancreatic cancer." (PMID 36553598, 2022). "The only exception was patient 04T, whose mutations (FAM71B- rs1404037352 and CSMD2- rs770364421) had lower mutated allele relative abundance in PF compared with the tumor sample, namely, 9.7% against 30.80% and 8.95% against 25%, respectively." (PMID 34070018, 2021). "Immunohistochemistry (IHC) analysis of tumor biopsy samples confirmed a loss of CSMD2 and enhanced EXT1 expression in tumor and PVTT cells, whereas MED30 expression was unchanged (data not shown)." (PMID 31200735, 2019). "In summary, CSMD2 expression was upregulated in most tumors, with moderate to high diagnostic efficiency, and its high expression was associated with high stage and poor prognosis in tumor patients." (PMID 36061177, 2022). "CSMD2 expression was also negatively correlated with infiltration of anti-tumor immune cells, including macrophages and natural killer cells, and was positively associated with immune evasion." (PMID 38259468, 2023). "TIMER2.0 database was employed to investigate the correlation between CSMD2 and immune cells in the tumor microenvironment and immune checkpoints." (PMID 36061177, 2022). "The mechanism of tumor immune regulation is highly complex, therefore, the relationship between CSMD2 and immunity requires further research." (PMID 36061177, 2022). "Conversely, the expression levels of CSMD2 in the tumor tissues of ACC, KICH, KIRP, PRAD, SKCM, TGCT, and THCA were lower than normal tissues." (PMID 36061177, 2022). "High levels of promoter methylation of CSMD2 and m6A methylation were found in tumor tissues or high CSMD2 expression tissues, suggesting the importance of abnormal methylation in tumor evasion of immune surveillance." (PMID 36061177, 2022). "The correlation between CSMD2 expression and immune cells in the tumor microenvironment was investigated." (PMID 36061177, 2022). "In this study, the correlation between CSMD2 expression and anti-tumor immune response and microenvironment was comprehensively analyzed." (PMID 36061177, 2022). "CSMD2 has shown activity as a tumor suppressor and TGFBI has been shown to inhibit tumor cell invasion, where loss of these genes may lead to tumor progression." (PMID 35565354, 2022). "The striking similarity of all three CSMD genes brought up the question of whether CSMD2 and 3 are also tumour suppressors." (PMID 36553598, 2022). "Enrichment analyses showed that CSMD2 might be located on the cell membrane, constitute a component of channel proteins, and participate in signal transduction between tumor cells." (PMID 36061177, 2022). "Our functional studies confirmed that one of these genes affected by two HBV_B2 integrations at chr1 and chr8, CSMD2, showed a reduced expression in HCC samples compared with the adjacent non-tumor tissues by IHC." (PMID 31200735, 2019). "Therefore, CSMD2 is speculated to promote tumor cells proliferation, migration and invasion through immune escape or immunosuppression rather than anti-tumor immune infiltration." (PMID 36061177, 2022).
neurodegenerative disease (2 papers, 2021 to 2024). A disorder of the central nervous system characterized by gradual and progressive loss of neural tissue and neurologic function. "As shown by the program results DE miR-3687, miR-612, miR-4261, miR-504-3p, miR-126-5p,and miR-411-5p bind to the mRNA of the B3GNT2, CSMD2, ATN1, CREBBP, ATXN1, EMIN4, and EFNA5 genes, which are associated with neurodegenerative diseases." (PMID 39049823, 2024).
psychiatric disorder (1 paper, 2019). A disorder characterized by behavioral and/or psychological abnormalities, often accompanied by physical symptoms. "Together, these results point toward a function for Csmd2 in development and maintenance of dendrites and synapses, which may account for its association with certain psychiatric disorders." (PMID 31068362, 2019).
CSMD2 also shares sentences with these, for which no sentence is quoted: breast carcinoma (3 papers); alcohol dependence (1); cognitive deficits (1); depression (1); head-neck squamous cell carcinoma (1); hematological malignancies (1); leukemia (1); Obesity (1); oligodendroglioma (1); prostate carcinoma (1); stomach (1); stomach adenocarcinoma (1); thyroid cancer (1).